PDGFRA (platelet derived growth factor receptor alpha)
Diseases named in the same sentence as PDGFRA in open-access papers (continued):
Sharing a sentence is not in itself a finding about the gene and the disease.
gastrointestinal disease (1 paper, 2017). A disease that occurs in the gastrointestinal system, excluding the hepatobiliary system. "Taken together, our data suggest that Cacna1g exclusively expressed in serosal PDGFRα+ cells is a new pathological marker for gastrointestinal diseases." (PMID 28806761, 2017).
intestinal diseases (1 paper, 2022). "This transcriptome data was added to our Smooth Muscle Genome Browser and Smooth Muscle Transcriptome Browser that both offer vital genetic references for PDGFRα+ cells that can aid further functional studies in intestinal diseases and physiology." (PMID 35560163, 2022). "Mucosal subepithelial PDGFRα+ cells (MuPαC) are important regulators in various intestinal diseases including fibrosis and inflammation." (PMID 35560163, 2022).
myopathies (1 paper, 2023). "Gal-3+ macrophages were also elevated in several human myopathies, including DMD, and were juxtaposed with PDGFRα+ stromal cells." (PMID 37418531, 2023).
PDGFRA also shares sentences with these, for which no sentence is quoted: hematologic malignancies (8 papers); chondrosarcoma (6); fibrosarcoma (4); inflammatory myofibroblastic tumor (4); acute leukemia (3); acute lymphoblastic leukemia (3); alveolar rhabdomyosarcoma (3); anaplastic oligodendroglioma (3); bone marrow disease (3); brain cancer (3); dermatofibrosarcoma protuberans (3); endocarditis (3); eosinophilic granulomatosis with polyangiitis (3); ependymoma (3); esophageal cancer (3); esophageal squamous cell carcinoma (3); ganglioglioma (3); mesothelioma (3); parasitic infections (3); pheochromocytoma (3); pleomorphic xanthoastrocytoma (3); primary myelofibrosis (3); primitive neuroectodermal tumor (3); Splenomegaly (3); Alpha-thalassemia (2); angiosarcoma (2); breast invasive carcinoma (2); ductal breast carcinoma in situ (2); experimental autoimmune encephalomyelitis (2); Gynecomastia (2).
A further 186 diseases each share a sentence with PDGFRA in 2 papers or fewer.